ZBP1 (Z-DNA binding protein 1)
Diseases named in the same sentence as ZBP1 in open-access papers (continued):
Sharing a sentence is not in itself a finding about the gene and the disease.
infection (continued). "Several previous studies have reported increased virus titers and disease severity in ZBP1−/− mice after infection with influenza virus, HSV-1, and MCMV." (PMID 31572318, 2019). "The protein levels of IL-5, IL-6, IFNγ, G-CSF, and MCP-1 (CXCL2) were significantly higher in ZBP1−/− mice compared to the WT mice at day 4 after infection." (PMID 31572318, 2019). "Primary mouse cortical neurons and mouse embryonic fibroblasts (MEFs) derived from ZBP1−/− mice produced higher virus titers compared to WT cells after infection with WNV NY99 and WNV Eg101." (PMID 31572318, 2019). "Our results are in agreement with previous studies demonstrating high levels of pro-inflammatory cytokines and chemokines in ZBP1−/− mice after infection with Toxoplasma gondii and influenza virus." (PMID 31572318, 2019). "The protein levels of interleukin (IL)-1α, TNFα, MIG (CXCL9), and IP-10 (CXCL10) were significantly higher in ZBP1−/− mice compared to the WT mice at day 2 after infection." (PMID 31572318, 2019). "WNV titers were significantly higher in ZBP1−/− mice as compared to WT mice at day 3 after WNV NY99 or WNV Eg101 infection." (PMID 31572318, 2019). "Similar to WNV, MEFs and neuronal cultures from ZBP1−/− mice produced significantly enhanced virus yields compared to those from WT mice after infection with the Asian or African strains of ZIKV." (PMID 31572318, 2019). "Nonetheless, significantly higher WNV RNA levels were detected in the brains of ZBP1−/− mice at day 8 after infection." (PMID 31572318, 2019). "Collectively, these findings support ZBP1 activation by specific cellular or viral RNAs induced following infection." (PMID 30050136, 2018). "ZBP1 is normally expressed at low levels in MEFs and showed the expected increase in WT MEFs after infection with either WT or mutant HSV1 at a high MOI." (PMID 30050136, 2018). "During natural infection, the RHIM-dependent association of ZBP1 and RIPK3 is blocked by MCMV M45, thereby avoiding premature cell death and supporting the production of progeny virus in support of dissemination and pathogenesis." (PMID 30050136, 2018). "The current evidence from influenza, vaccinia, MCMV, and now HSV1 that transcripts accumulating during infection are the most likely PAMP that interacts with ZBP1 under natural conditions." (PMID 30050136, 2018). "Using reconstitution and knock‐in models, we report that mutation of key amino acids involved in Z‐DNA/RNA binding in ZBP1's ZBDs prevented necroptosis upon infection with mouse cytomegalovirus." (PMID 28716805, 2017). "Previous work suggested that the type of cell death triggered by ZBP1 upon MCMV‐M45mutRHIM infection is necroptosis." (PMID 28716805, 2017). "Cell viability following TZ treatment or MCMV‐M45wt infection was comparable between parental Zbp1−/− and ZBP1‐reconstituted cells." (PMID 28716805, 2017). "IE3 depletion led to diminished cell death upon infection of NIH3T3 cells expressing wild‐type ZBP1 with MCMV‐M45mutRHIM." (PMID 28716805, 2017). "In contrast, viability upon MCMV‐M45mutRHIM infection was much higher in IFN‐treated Zbp1−/− primary MEFs, despite comparable expression of RIPK3 and MLKL." (PMID 28716805, 2017). "The identification of CMPK2 and ZBP1 as central hub genes highlights their potential roles in coordinating mitochondrial stress responses and regulated cell death mechanisms during the early containment phase of infection." (PMID 41465783, 2025). "In contrast, after AC infection, the percentage of apoptotic macrophages in mouse brain increased from 0% to 31% (p < 0.0001), while a significant decrease (15%, p < 0.001) in apoptotic macrophages was detected in infected Zbp1 knockout mice." (PMID 39853924, 2025). "We detected increased levels of ZBP1 as early as day 1 post infection (mean fold change = 4.1)." (PMID 40416961, 2025).
infection (continued). "It has been demonstrated that ZBP1‐activated innate immunity, which includes NF‐κB signalling and the type‐I interferon (IFN‐I) response, is a crucial line of defence against pathogenic infection." (PMID 41299204, 2025). "Lungs were collected from ZBP1−/− and WT mice following infection with MA10." (PMID 40416961, 2025). "Furthermore, ZBP1‐mediated PANoptosis has conflicting effects on tumour immunity, auto‐inflammatory illnesses, and anti‐infection." (PMID 41299204, 2025). "Upon infection, ZBP1 recognized viral RNA or viral proteins, to activate RCD pathways." (PMID 40977695, 2025). "Future studies should prioritize deciphering the molecular “inflammatory switch” mechanism governed by ZBP1 and explore the development of therapeutic strategies targeting specific inflammatory pathways to control refractory infections involving HAR E. faecalis." (PMID 41471852, 2025). "Furthermore, Gutierrez-Alvarez and others discovered that ZBP1 was a crucial gene expressed in both human and mice lung cells after infection with a strain of MERS-CoV and with SARS-CoV." (PMID 38714196, 2024). "The results revealed a significant increase in ZBP1 protein level only at 16 hours post-infection." (PMID 39850894, 2024). "HSV-1(ICP6mut) infection triggers endogenous ZBP1-driven necroptosis in human cells." (PMID 39345610, 2024). "SVA infection significantly up-regulated the expression of ZBP1 in 3D4/21 cells." (PMID 38822277, 2024). "Notably, ZBP1-Zαβ condensates were observed in the nucleus during infection with DNA virus HSV or RNA virus IAV." (PMID 38982083, 2024). "The results showed that the levels of p-RIPK3 and p-MLKL were significantly increased in the ZBP1 overexpression PTCs comparing with the vector control transfected cells (Vec) during PPV infection, while the expression levels of RIPK3, MLKL, and Caspase-8 did not significantly change." (PMID 39614405, 2024). "Also, the involvement of ZBP1 in modulating lethality following IAV-infection shows various outcomes." (PMID 38778049, 2024). "Thus, we infected both WT and ZBP1 KO mice and then assessed the bacterial load in the spleen at 2 and 4 weeks post-infection (wpi)." (PMID 39850894, 2024). "Similarly, R1-ICR-3 also reduced RIPK3 recruitment by endogenous ZBP1 triggered by HSV-1(ICP6mut) infection in HS68 cells." (PMID 39345610, 2024). "Furthermore, we evaluated the CFU counts following 8 hours and 16 hours of infection in macrophages derived from ZBP1 and WT mice." (PMID 39850894, 2024). "In addition, the expression of ZBP1 is upregulated in the infection of a variety of viruses, such as influenza virus, coxsackievirus A6, and HSV-1." (PMID 38822277, 2024). "The R1 (ICP6) encoded by herpes simplex virus (HSV)-1 and HSV-2 blocks necroptosis in human cells and naturally prevents virus-induced necroptosis triggered very early after infection of human cells by preventing ZBP1 recruitment of RIPK3 using a mechanism very much like MCMV M45." (PMID 39772130, 2024). "Thus, to a certain extent, these findings together explain the activation of ZBP1 during infection with IAV." (PMID 36845119, 2023). "The function of ZBP1 in transcriptional responses in more complex scenarios including natural infections will likely be more difficult to dissect given the redundancy with other ubiquitously expressed nucleic acid sensors that specialize in the induction of transcription of antiviral genes." (PMID 37450010, 2023). "These discrepancies may be caused by experimental parameters that determine the severity of disease such as the viral strain, infectious dose, genetic background of Zbp1 knockout mice, and the route of infection." (PMID 37450010, 2023). "By day 6 after infection, ZBP1 and MLKL mRNA levels were upregulated ~50-fold in the brains." (PMID 35215199, 2022).
infection (continued). "Furthermore, it has been reported that ZBP1 is a vital gene expressed following infection of human and mice lung cell with an isolate of Middle East Respiratory Syndrome (MERS)-CoV and SARS-CoV-1 (Mamoor, 2020)." (PMID 36320810, 2022). "In addition, the protein and mRNA levels of ZBP1 and pMLKL also increased 1 to 3 days after infection, which directly demonstrated that ZBP1 induced by SARS CoV-2 mediates the occurrence of necroptosis." (PMID 36615244, 2022). "ZBP1 and the IFI16 have also been associated during pathogen infection." (PMID 35626718, 2022). "ZBP1 activated innate immunity, including type-I interferon (IFN-I) response and NF-κB signaling, constitutes an important line of defense against pathogenic infection." (PMID 36142136, 2022). "In addition, ZBP1-mediated PANoptosis is a double-edged sword in anti-infection, auto-inflammatory diseases, and tumor immunity." (PMID 36142136, 2022). "The levels of ZBP1 increased at 24 and 48 h after infection." (PMID 35215199, 2022). "To determine if RIPK1 mediates MLKL phosphorylation in ZBP1-deficient astrocytes following infection, we treated ZBP1+/+ and ZBP1−/− derived astrocytes with the RIPK1 inhibitor, GSK963, during infection with the HSV-1(MacIntyre), HSV-1(F)-ICP6-RHIM Mut, and HSV-1(F) strains." (PMID 35549723, 2022). "Data demonstrating sensing of VACV E3LΔ83N infection by ZBP1 suggests that the Zα domains of E3 and ZBP1 may be competing with each other for binding to a Z-form nucleic acid in infected cells." (PMID 35203445, 2022). "Infection with T. gondii alone caused little LDH release in each BMDM genetic background, but stimulation with TNF and Z-VAD-FMK (a pan-caspase inhibitor that drives necroptosis) caused a similar increase in LDH release in WT and ZBP1−/− BMDM." (PMID 33526566, 2021). "Interestingly, infection of ZBP1−/− mice with WNV Eg101 was lethal resulting in 100% mortality, suggesting that ZBP1 is required for survival after WNV infection." (PMID 31572318, 2019). "In primary mAECs, ZBP1 could be induced by H1N1 24 h post-infection and H1N1 infection at MOI of 5 was enough for ZBP1 induction, which correlated with the IAV-induced p-MLKL at Ser345." (PMID 31440477, 2019). "Interestingly, infection of ZBP1−/− mice with WNV Eg101 was highly lethal and resulted in 100% mortality." (PMID 31572318, 2019). "Therefore, we measured the protein levels of IFN-α in the serum (day 3 after infection) and brain homogenates (day 8 after infection) of WT and ZBP1−/− mice using ELISA." (PMID 31572318, 2019). "We next sought to characterize whether a ZBP1/RIPK3 necrosome-like complex was formed during infection." (PMID 30050136, 2018). "Altogether, ZBP1 emerges a critical and specific sensor of infection by many mammalian viruses." (PMID 30050136, 2018). "MCMV‐M45mutRHIM infection predisposes NIH3T3 cells to TNF‐induced cell death independent of ZBP1 expression (Fig EV4E)." (PMID 28716805, 2017). "In contrast, ZBP1‐Zα1α2mut‐expressing cells displayed higher viability after infection and behaved similar to the parental Zbp1−/− cells, while ZBP1‐Zα1mut and ZBP1‐Zα2mut cells showed intermediate phenotypes, with a greater contribution to cell death of the Zα2 domain." (PMID 28716805, 2017). "MCMV‐M45mutRHIM infection induced pronounced cell death in ZBP1 wild‐type reconstituted cells." (PMID 28716805, 2017). "Cell death induced by MCMV‐M45mutRHIM in wild‐type ZBP1‐expressing cells was also observed by live‐cell microscopy using the dye SytoxGreen, which stains cells that have lost membrane integrity, and cell death was detected from 8 h post‐infection onwards." (PMID 28716805, 2017). "Moreover, infection with the M448R-deficient ASFV mutant leads to increased IRF1 protein stability and elevated expression of IRF1 target genes, including OAS1, OAS2, and ZBP1." (PMID 42262133, 2026).
infection (continued). "Finally, using Zbp1‐knockout mice as a model, flow cytometry was applied to assess immune functions of brain macrophages and characteristics of the immune microenvironment of brain during the infection." (PMID 39853924, 2025). "Finally, we examined the level of ZBP1 protein stimulated by the infection." (PMID 39850894, 2024). "Additionally, ZBP1 also contributes to Unfolded Protein Response (UPR) activation during infection." (PMID 39850894, 2024). "Moreso, ZBP1 was found associated with RNA during MCMV-M45mutRHIM infection and induction of cell death required RNA synthesis but not viral DNA replication, implicating a role for Z-RNA in virally induced necroptosis, similarly to what we suggest for VACV E3LΔ83N." (PMID 35203445, 2022). "During E30 infection, genes associated with the type I IFN signaling pathway (Isg15, Mx1, Mx2, Sp100, Ifit1, Ifit3, Ifih1, Irf7, Irf9, guanylate-binding proteins 2 [Gbp2], and Stat1) and defense response to viruses (Ddx58, Ddx60, Zbp1, Oas2, Nlrc5, and Eif2ak2) were significantly upregulated." (PMID 36147849, 2022). "Furthermore, MCMV-M45mutRHIM infection is successfully cleared in wt mice, but not in knock-in mice expressing ZBP1 with mutated Zα domains, suggesting a role for Z-NAs in clearing MCMV infection." (PMID 35203445, 2022). "Monolayers of ZBP1-expressing or control HT-29s were infected at a ratio of 1 infected HT-29 (wild type) to 10 uninfected (ZBP1/control) cells with the VZV BAC-derived parent strain or the RHIM mutated virus (VZV-RHIMmut) and plaque formation was assessed at 72 h post-infection." (PMID 32649716, 2020). "Monolayers of ZBP1-expressing or control ARPE-19 cells were infected at a ratio of 1 infected ARPE-19 (wild type) to 10 uninfected (ZBP1/control) cells, with the VZV BAC-derived parent strain or the RHIM mutated virus (VZV-RHIMmut), and plaque formation was assessed at 72 h post-infection." (PMID 32649716, 2020). "The interactions of ASC with molecular components of PANoptosis (e.g., ZBP-1, AIM2, Pyrin, RIPK1, caspase-1, and RIPK3) are observed following infection, and ASC deletion leads to decreased expression of ZBP-1, Pyrin, and caspase-1." (PMID 41304245, 2025). "BST2, ZBP1, CXCL11, and IFITM1 were involved in protein binding, and they are also broadly engaged in biological processes related to IFNs and responding to infections." (PMID 39874350, 2025). "Upon infection, host cells detect viral RNA via PRRs such as TLRs, RIG-I-like receptors, cGAS–STING, ZBP-1, and NLRs." (PMID 40977695, 2025). "Our findings uncovered a novel mechanism by which ASFV induces macrophage necroptosis by facilitating Z-DNA accumulation and ZBP1 necrosome assembly, providing significant insights into the pathogenesis of ASFV infection." (PMID 38952452, 2024). "As expected, in Zbp1+/+ BMDMs, Caspase-1 was mildly activated following infection with PRV-WT and PRV-ΔVP22R but strongly activated after infection with PRV-ΔVP22." (PMID 39475237, 2024). "Among the PRR family, DNA sensors including ZBP1, AIM2, RNA polymerase III, IFI16, DDX41, and cGAS, are critical in identifying exogenous nucleic acid stimuli during pathogen infections, initiating subsequent antiviral and antibacterial immune responses." (PMID 38982083, 2024). "Subsequently, it has been documented that upon infection of host cells with influenza A virus (IAV), ZBP1 recognizes the IAV genome and in turn activates host RIPK3 kinase, which induces cell death through the MLKL-driven necroptosis pathway." (PMID 38100396, 2024). "ZBP1 is found to interact with RIPK3 and thereby promotes the execution of necroptosis during infection with HSV-1, MCMV and influenza A virus." (PMID 38400065, 2024). "During infections with HSV-1, AIM2 interacts with the MEFV innate immunity regulator (MEFV, also known as Pyrin or [TRIM20]) and ZBP1 to drive inflammatory signaling and PANoptosis." (PMID 38932258, 2024).
infection (continued). "Western blotting analysis further confirmed the upregulation of ZBP1 and NLRP6 at the protein level in all five cell lines upon oHSV infection." (PMID 38693119, 2024). "Consistently, in Zbp1+/+ BMDMs, Caspase-1 was mildly activated following infection with PRV-WT, ΔVP22 (1–50 aa), or ΔVP22R but strongly activated upon infection with PRV-ΔVP22 and ΔVP22 (51–246 aa)." (PMID 39475237, 2024). "As indicated, DAI or ZBP1 (specifically Zα domain) acts as a cytosolic DNA sensor and can participate in inducing the apoptosis while IvA infection is initiated." (PMID 37773712, 2023). "Compared with WT BMDMs, the activation of CASP1/GSDMD/GSDME, CASP8/3/7, and RIPK3/MLKL in Mefv–/– and Zbp1–/– BMDMs decreased after infection with HSV1 or F. novicida, and completely inactive in Aim2–/– and Mefv–/–Zbp1–/– BMDMs." (PMID 36845112, 2023). "At the same early time of 12 h post-infection, the RIPK3 KO BMDMs started to diverge from the ZBP1 KO cells and began to show the activation of caspases and GSDMD and GSDME." (PMID 38005819, 2023). "As a transcriptional regulator of ZBP1, IRF1 undoubtedly acts as an upstream regulator of PANoptosis during infection with pathogens such as IAV." (PMID 36845112, 2023). "In the host immune response induced by infection, AIM2 can form PANoptosome with ZBP1 and another type of inflammasome Pyrin." (PMID 38203518, 2023). "In addition, other members of the Orthomyxoviridae family, such as seasonal strains of IAV and IBV but not the Paramyxoviridae family, also produce the nuclear Z-RNA, and whether ZBP1 also mediates similar PANoptosis against other orthomyxoviruses infection requires further verification." (PMID 36142136, 2022). "High dose infection or late infection with SARS-CoV-2 induce IFN-α/γ responses and the expression of ZBP1." (PMID 36142136, 2022). "Here, we have investigated the ability of this sensor to limit infection in astrocytes derived from ZBP1+/+ and ZBP1−/− mice." (PMID 35549723, 2022). "Interestingly, inhibition of apoptotic pathways appears to permit HSV-induced necroptosis in astrocytes that is independent of ZBP1, as treatment with a pan caspase or a caspase-8 inhibitor did not reduce levels of phosphorylated MLKL following infection in ZBP1-deficient cells." (PMID 35549723, 2022). "Since the discovery that ZBP1, via RIPK3, induces necroptosis during murine cytomegalovirus (MCMV) infection, its role in cell death during infection and embryonic development has been well established." (PMID 36268590, 2022). "Z-DNA binding protein 1 (ZBP1) has been found to promote pyroptosis and necroptosis upon sensing infection with fungus." (PMID 35958626, 2022). "Previous work has shown that DVGs are potent ligands for RIG-I, as well as other PRRs, such as ZBP1, which can drive necroptosis, and the production of cytokines coincides with DVG emergence following infection with influenza virus." (PMID 36226985, 2022). "RHIM-mediated signaling by RIPK1, TRIF, ZBP1, and RIPK3 culminating in necroptosis is a key pathway utilized by cells in inflammation and infection settings." (PMID 36040212, 2022). "In the setting of pathogens infection, RIPK1 is an important member of the ZBP1-PANoptosome and the key to ZBP1-mediated PANoptosis." (PMID 36142136, 2022). "To accomplish this, we treated ZBP1+/+ and ZBP1−/− derived astrocytes with both a RIPK3 inhibitor (GSK872) and a pan caspase inhibitor (zVAD-FMK) following infection with HSV-1(MacIntyre), HSV-1(F), and HSV-1(F)-ICP6-RHIM Mut strains." (PMID 35549723, 2022). "Next, we sought to understand the molecular relationship between AIM2, Pyrin and ZBP1 in inducing inflammatory cell death, PANoptosis, during HSV1 and F. novicida infections." (PMID 34471287, 2021). "Therefore, identification of ZBP1-regulated TRIFosome formation, CASP8 activation, and IL-1β production provides novel points of regulation that could be relevant in the context of various pathogenic infections." (PMID 33397971, 2021).